C9orf152 (chromosome 9 open reading frame 152)
Synonyms: bA470J20.2
Tractability: No criterion of Open Targets' tractability assessment is met for any kind of drug.
Gene: Protein-coding gene on chromosome 9 (110,190,048 to 110,208,159, reverse strand). Ensembl gene ENSG00000188959.
Subcellular location (Human Protein Atlas): Nucleoplasm; Nucleoli
Gene Ontology:
Molecular function: protein binding
Genetic constraint (gnomAD): Loss-of-function variants: 6 observed, 6.25 expected, observed/expected ratio (o/e) 0.96, 90% interval 0.52 to 1.74. That is too few expected variants to judge how well the gene tolerates losing a copy. Missense variants: 193 observed, 179.17 expected, observed/expected ratio (o/e) 1.08, 90% interval 0.96 to 1.21. Synonymous variants: 75 observed, 73.37 expected, observed/expected ratio (o/e) 1.02, 90% interval 0.85 to 1.24.
Homologues: Orthologues: chimpanzee C9H9orf152 (98% identical), macaque C15H9orf152 (75% identical), pig C9orf152 (74% identical), dog C9orf152 (69% identical), rabbit C9orf152 (69% identical), guinea pig C9orf152 (69% identical), mouse D630039A03Rik (62% identical), rat C5h9orf152 (62% identical), tropical clawed frog c6h9orf152 (26% identical).
Diseases named in the same sentence as C9orf152 in open-access papers:
C9orf152 is named in the same sentence as 2 diseases in open-access papers, as found by Europe PMC text mining. Sharing a sentence is not in itself a finding about the gene and the disease. The quoted sentences say what the papers report.
oesophageal cancer (1 paper, 2023). "The top GPR176-correlated genes (PDPH, KIREL1, CLEC12A-AS1, CERCAM, IKBIP, LOX, COL5A2 and ELF3) were more highly expressed in oesophageal cancer than in normal tissue (p < 0.05), but the converse was true for C9orf152 and MT-TP (p < 0.05)." (PMID 37584712, 2023).
tumor (1 paper, 2024). "Additionally, the genes in the Light-Yellow module include SPDEF, ELAPOR1, C9orf152, PLPP2, and SCGB2A1 and may be involved in several biological processes including tumor immunity and epithelial cell differentiation." (PMID 39596419, 2024).